CD44 (CD44 molecule (IN blood group))
Diseases named in the same sentence as CD44 in open-access papers (continued):
Sharing a sentence is not in itself a finding about the gene and the disease.
glioblastoma (continued). "To determine if these miRNAs are more abundant in CD44-enriched EVs (SEC + CD44 EVs) compared to miRNAs isolated from total serum, we studied the levels of these microRNAs in the serum of glioblastoma patients (n = 55) at the Q3 time point." (PMID 33003586, 2020). "Phospholipase D1 elevation positively correlated with the level of CD44 and poor prognosis in glioblastoma patients." (PMID 32725633, 2020). "Nine proteins, i.e., tubulin 2B chain, CD59, far upstream element-binding, CD44, histone H1.4, caldesmon, osteopontin, tropomyosin chain and metallothionein-2, marked the core of newly diagnosed glioblastoma with respect to tumor periphery." (PMID 33374813, 2020). "We found that overexpression of CD44 increased tumor cell proliferation, and overexpression of CD44 abolished the effects of galangin on proliferation in glioblastoma cells." (PMID 31528214, 2019). "Both glioblastoma cell migration and invasion promoted by the overexpression of CD44 were abolished by treatment with galangin." (PMID 31528214, 2019). "Silencing EMP1 expression in glioblastoma cells inhibits their proliferation and invasiveness, as well as the expression of CD44 and matrix metalloprotease (MMP)-2." (PMID 31652725, 2019). "RFX1 directly downregulated CD44 expression, affecting the ability for proliferation, survival, and invasion in glioblastoma cells." (PMID 30857550, 2019). "Prominent biomarkers of mesenchymal glioblastoma cells in neurosphere culture included CD44, BCL2A1, and LYN46–48." (PMID 29445239, 2018). "Knockdown of CD44 in glioblastoma cell lines decreases tumor growth and sensitizes them to cytotoxic drugs." (PMID 29914429, 2018). "CD44 expression in glioblastomas is correlated with cancer stem cell phenotype, tumor aggressiveness, and poor survival." (PMID 29246031, 2017). "Consistent with a role of CD44, MMP9 and CHI3L1 in aggressive glioblastoma properties, low expression of the three genes was associated with better outcome in TCGA samples." (PMID 28036297, 2017). "In these studies CD44 was knocked-down in glioblastoma cells, and the cells were cultured on hydrogels of methyacrylated HA37." (PMID 29184125, 2017). "In a previous study, Yoshida indicated that the overexpression of CD44 was important for the growth and survival of glioblastomas, and the monoclonal anti-CD44 antibody affects the migration of glioblastoma cells." (PMID 28191466, 2017). "Phospho-c-Jun activation by Anisomycin treatment in primary glioblastoma-derived cells attenuates the aggressive features of mesenchymal glioblastomas and leads to promoter methylation and downregulation of key mesenchymal genes (CD44, MMP9 and CHI3L1)." (PMID 28036297, 2017). "It has also been recently shown that CD44 expression, being a marker of TNFalpha/NFkB-induced mesenchymal differentiation of glioblastoma, correlates with poor radiation response and shorter survival." (PMID 26188123, 2015). "The levels of HA and its receptor CD44 in tumor cells are predictive of malignancy and often correlate with cancer aggressiveness in patients with glioblastoma, breast, prostate and non-small cell lung cancers." (PMID 23855374, 2013). "Overexpression of CD44, a transmembrane glycoprotein, has been reported in glioblastoma, breast, prostate, cervical, ovarian and head and neck cancer." (PMID 23855374, 2013). "CD44-EGFR interaction in glioblastoma cells enhanced HA-mediated phosphorylation of extracellular signal regulated kinases 1 and 2 (ERK1 and ERK2)." (PMID 23855374, 2013). "Previous studies have shown that CD44 is redistributed to lamellipodia and subsequently cleaved and shed from the cell surface when RhoA is over-activated in human glioblastoma cells (U251MG)." (PMID 22363471, 2012). "Considering our data, and recent literature demonstrating mesenchymal differentiation of glioblastoma cells, we defined the CD44+, GFAP-, MAP2- population of glioblastoma cells as mesenchymal." (PMID 19216795, 2009).
glioblastoma (continued). "In our culture model, a population of glioblastoma cells was able to form aggregates composed of cells with multilineage phenotype, i.e. showing expression of: CD44, Vimentin, GFAP, Nestin, Beta III-tubulin, MAP2, Fibronectin and SOX-2, but not CD133." (PMID 19216795, 2009). "SPP1 (OPN) is a ligand of CD44 that is secreted by both myeloid and glioblastoma cells." (PMID 40191733, 2025). "Furthermore, significant up-regulation of CD44 is found in glioblastoma cells of pseudopalisading necrosis." (PMID 40191733, 2025). "This latter study, which was performed with human glioblastoma cell lines, suggests a positive feedback mechanism in which hypoxia regulates CD44, which, in turn, may regulate more hypoxia-related genes." (PMID 38247821, 2024). "Interestingly, both CD44 and Sox2 are markers of radiation resistance in primary glioblastoma cultures, but CD44 expression correlates positively with radioresistance, while the Sox2-positive subpopulation shows the highest radiosensitivity." (PMID 38672482, 2024). "Further, CD44 is most commonly associated with glioblastoma stemness, which is related but not identical to the mesenchymal phenotype." (PMID 38337036, 2024). "Moreover, inhibiting CD44 dimerization via verbascoside has been reported to suppress stem cell‐like cell properties and tumor cell growth in glioblastoma." (PMID 38783892, 2024). "The transmembrane receptor CD44 was previously shown to facilitate glioblastoma cell migration and may integrate adhesive and signaling activities to modulate the migratory processes." (PMID 38941039, 2024). "This makes CD44 an important therapeutic target in the context of glioblastoma." (PMID 38611849, 2024). "Furthermore, flow cytometric analysis of membrane Glioblastoma stem cell markers (GSC) revealed that GBM cells express higher levels of CD44 compared to CD133." (PMID 39408757, 2024). "However, we have shown that RFX1 can induce apoptosis and inhibit cell proliferation of glioblastoma cells via inhibiting CD44 and related signalling molecules." (PMID 39636301, 2024). "Moreover, CCNB1, MAPK7, CD44, and CDC42 oncogenes have been associated with patients’ clinical outcomes in glioblastoma and it has been identified in simulation studies for druggable candidates of SJ10." (PMID 39409884, 2024). "For instance, CUL4A mediates the ubiquitination of LATS1 to regulate YAP activity in hepatocellular carcinoma, AGK inhibits the activation of the Hippo pathway proteins in GC38 and CD44 functions upstream of the Hippo signalling pathway and attenuates its activation in glioblastoma." (PMID 37555915, 2023). "Furthermore, glioblastoma stem cell (GSCs, X01) membrane CM (X01) had CD44, one of stem markers, as well as EpCAM, both of which were helpful to target homotypic cells." (PMID 37507371, 2023). "microRNAs participating in regulation of the activites of CD44 in glioblastoma." (PMID 37835592, 2023). "CD44 also functions as a receptor site for hyaluronic acid (HA) in glioblastoma patients." (PMID 36185622, 2022). "Interestingly, verbascoside has been reported to inhibit the activity of CD44 in glioblastoma cell lines." (PMID 35778717, 2022). "Hence, we analyzed the expression of CD44 in publicly available glioblastoma TCGA datasets using the ULCAN." (PMID 36231019, 2022). "Circ-CD44 expression was decreased in glioblastoma multiforme (GBM) tissues and primary GBM cells." (PMID 35883576, 2022). "CD44 thus holds a therapeutic potential as stroma-directed therapy target for glioblastoma." (PMID 35992852, 2022). "CD44 is overexpressed in mesenchymal subtype of glioblastoma." (PMID 36185622, 2022). "In this study, our results revealed that interfering with HA synthesis in glioblastoma or inhibiting the binding of HA to CD44 on macrophages inhibits M2 macrophages polarization and activates M1 macrophages polarization by regulating STAT3 and STAT1 phosphorylation." (PMID 35410993, 2022).
glioblastoma (continued). "According to our results, we considered that disruption of glioblastoma HA synthesis or blocking the binding of HA to CD44 on macrophages could modulated the phenotype of macrophages." (PMID 35410993, 2022). "In glioblastoma cells, Galangin (3,5,7-trihydroxyflavone), a natural flavonoid in plants, was observed to inhibit CD44 and EMT through vascular endothelial growth factor (VEGF) downregulation, suppressing the proliferation, invasion migration and angiogenesis of tumour cells." (PMID 34944493, 2021). "A previous study showed that the expression of CD44 in glioblastoma may be heterogeneous, and the tumorigenicity of primary GBM differs between CD44low/CD133high and CD44high/CD133low for gene expression profiles." (PMID 32232385, 2020). "Furthermore, in a recent report, CD44 was reported to be crucial for microtentacles, specific protrusions formed by glioblastoma cells in hyaluronan-rich extracellular matrix (ECM)." (PMID 32679746, 2020). "Subsequently, the molecular heterogeneity among tumors may affect the prognostic value of CD44 in glioblastoma." (PMID 32232385, 2020). "However, the analysis of SEC-enriched serum-derived EVs from HV showed significantly lower CD44 levels compared to EVs from the serum of glioblastoma patients, indicating that CD44-positive EVs are enriched and highly relevant in glioblastoma patients." (PMID 33003586, 2020). "Indeed, in the REMBRANDT brain cancer dataset, for example, the expression levels of CD44 were increased in most glioblastoma (GBM) cases, but they were kept lower in normal brain tissues." (PMID 32977522, 2020). "Due to a high upregulation of CD44 in glioblastoma patients compared to HV, we hypothesized that the immunoprecipitation of EVs with CD44 would lead to an enrichment of glioblastoma-specific EVs." (PMID 33003586, 2020). "Moreover, we introduce a novel approach for separating and enriching glioblastoma-specific EVs by combining size-exclusion chromatography and immunoprecipitation with CD44 as a unique target antigen." (PMID 33003586, 2020). "We further investigated whether these effects are due to the regulation of EMT and angiogenesis via the modulation of CD44 expression by galangin in glioblastoma." (PMID 31528214, 2019). "CD44 has been reported to be an oncoprotein in glioblastoma." (PMID 31528214, 2019). "The results of in vivo studies are consistent with results of in vitro studies, demonstrating that galangin may play a critical role in the suppression of glioblastoma growth in an intracranial tumor model via inhibition of CD44-mediated EMT and angiogenesis." (PMID 31528214, 2019). "Finally, we investigated the relation of the identified CD44+/CD133+/ITGA6+/CD36+ signature to the four glioblastoma molecular subtypes (mesenchymal, neural, proneural, and classical) as well as the isocitrate dehydrogenase 1 (IDH1) status." (PMID 30467961, 2019). "We also observed that the upregulation of CD44 enhanced glioblastoma cell migration and invasion." (PMID 31528214, 2019). "Theoretically, it might be that after all these experiments, cells with the CD44+/CD133+/ITGA6+/CD36+ signature can indeed be described as a phenotype especially characteristic of stem‐like glioblastoma cells." (PMID 30467961, 2019). "Moreover, CD44 - glioblastoma multiforme stem cell marker – is also highly expressed in the TCL self-renewing cells." (PMID 29568390, 2018). "To determine whether KW10 and MTA10 cell cultures represented distinct glioblastoma subtypes, we performed immunoblotting of the mesenchymal marker CD44 in both cultures." (PMID 28744448, 2017). "CD44 expression was primarily observed in the membrane of glioblastoma cells." (PMID 28279210, 2017). "We used human glioblastoma patient–derived primary neurosphere cells, named “1123”, which has been shown to possess stem cell-like characteristics including a high level of CD44 expression, self-renewal capability and tumorigenicity when implanted in mouse brain." (PMID 25885522, 2015).
glioblastoma (continued). "In glioblastoma, CD44 expression conferred growth advantages and therapeutic resistance and it remains to be resolved whether analogous mechanisms are also active in MB, in particular in the context of c-Met interaction with CD44v6." (PMID 25625039, 2015). "There is only one example of the use of CD44 as a stem cell marker in glioblastoma." (PMID 22685459, 2012). "Since we evidenced in glioblastomas that the amounts of CD44 are high and that the amount of SIRT1 that inactivates EP300 is low, we can assume that this situation may facilitate activation of STAT3 by acetylation." (PMID 21655185, 2011). "Therefore, in this study for the first time, the expression level of all members of the HER family, EGFRvIII, CD44, and CD109 was determined at different cut of values in patients with glioblastoma as well as their association with the patient’s overall survival." (PMID 40227788, 2025). "In addition, we confirmed these findings by overexpressing CD44 in human glioblastoma cells." (PMID 31528214, 2019). "Accumulating evidence suggests that the stem cell markers CD133 and CD44 indicate molecular subtype in Glioblastoma Multiforme (GBM)." (PMID 25749043, 2015). "However, localisation of CD44 outside lipid rafts in human glioblastoma cells has been shown to induce metalloproteinase-mediated CD44 shedding and tumour cell migration, which was further confirmed after membrane cholesterol modulation with methyl-β-cyclodextrin, filipin and simvastatin." (PMID 24512624, 2014). "While the positive selection for EpCAM is useful for most epithelial cancers, it is not suitable for glioblastoma because neural tumors usually lack EpCAM expression, but it has potential for glioblastoma, when the right markers will be applied; Specific CD44 variants may be an option." (PMID 41514523, 2025). "Another ECM component is HA, which activates CD44, a cell surface adhesion protein, stimulating the synthesis and secretion of additional HA, leading to upregulation of MT1-MMP, thus promoting glioblastoma cell infiltration." (PMID 41208963, 2025). "CD44, together with MMP14 and BCG, is part of a subpopulation of extracellular vesicles for glioblastoma invasion." (PMID 41440277, 2025). "Glioblastoma patients exhibited significant upregulation of CD29, CD44, CD81, CD146, CqQA, and histone H3 compared to healthy volunteers, with additional upregulation of C1QA, CD44, and histone H3 observed to those with stable disease." (PMID 41373835, 2025). "Taken together, our results suggest that the co-expression of different members of the HER family, with EGFRvIII, CD44, and CD109 is common in patients with glioblastoma." (PMID 40227788, 2025). "EVs can also carry CD44 and CD133, biomarkers of glioblastoma,a fatal brain tumor characterized by its aggressive nature and poorprognosis." (PMID 40720603, 2025). "In this study, our aim was to examine the relative expression and prognostic significance of all members of the HER family, the type III EGFR mutant (EGFRvIII), and the putative stem cell markers CD44 and CD109 in patients with glioblastoma." (PMID 40227788, 2025). "The use of CAR-T cells in glioblastoma is based on targeting the tumor-specific or tumor-enriched antigens like IL-13Rα2, EGFR/EGFRvIII, HER2, CD70, B7-H3, and CD133/CD44." (PMID 41208963, 2025). "In Zhao2019_PD1-Glioblastoma and Gide2019_PD1+CTLA4-Melanoma cohorts, high-CD44-expression patients exhibited the unfavorable OS relative to low-CD44-expression counterparts, representing a worse immunotherapy outcome." (PMID 38590654, 2024). "Studies have shown that EVs derived from the serum of glioblastoma patients exhibit upregulated levels of specific proteins such as C1QA, CD29, CD44, CD81, and CD146, as well as histone H3 compared to EVs from healthy individuals." (PMID 37568620, 2023). "In glioblastoma, increased MSN expression increased the expression of β-catenin, CD44, ICAM-1, and MMP-2.28." (PMID 37446127, 2023).
glioblastoma (continued). "iPSC induced with U87MG CSCs CM were found to overexpress CSC-specific markers CD133, CD44, ABCG2 and ABCC2, which confirmed these cells as iPSC-derived glioblastoma stem cells (iPSC-GSCs); these markers are more than monolayer U87MG, as observed." (PMID 37509281, 2023). "We found a similar correlation between CD44, FUT4 (CD15) and ABCC3 expression across glioblastoma patient datasets." (PMID 36585418, 2022). "Its effect on a subpopulation of GBM cells exhibiting glioblastoma stem cell (GSCs)-like characteristics revealed a reduced expression of Oct4, Sox2, CD133, CD44, and a decrease in ALDH+, Nestin+ and CD44+ cells." (PMID 36231019, 2022). "HA promotes glioblastoma migration by regulating glioblastoma invasion via the receptor for hyaluronan-mediated motility (RHAMM) and CD44, as well as other mechanical and topographical signals." (PMID 35565282, 2022). "A similar study using glioblastoma cell lines proved that RFX1 overexpression led to decreased cell invasion, migration, and proliferation mediated by direct targeting of CD44." (PMID 33964962, 2021). "Within the glioblastoma TME, CCL5 produced by GAMs, mesenchymal stem cells (MSCs) and tumour cells signals through CCR1, CCR5 and CD44." (PMID 33803414, 2021). "CD44 depletion collectively with EGFR inhibition results in synergistic and robust glioblastoma cell death." (PMID 34944493, 2021). "Produced by glioblastoma tumour cells and GAMs, OPN engages with integrin proteins such as αVβ5 and CD44." (PMID 33803414, 2021). "We prepared four types of glioblastoma stem-like cells, MGG4, MGG8, MGG18, and MGG23, and we first analyzed the expression levels of CD44." (PMID 32977522, 2020). "Ablation of CD70 in glioblastoma cells reduced genes correlated with tumor epithelial mesenchymal transition (EMT), such as SOX-2 and CD44, and inhibited the migration and growth of the tumor." (PMID 32429463, 2020). "A previous study showed that MSN was frequently overexpressed in high‐grade glioblastoma, and MSN interacted and colocalized with CD44." (PMID 32941674, 2020). "High expresssion of CD44 and lower expression level of CNTN3 were both related to the poor prognosis of glioblastomas." (PMID 32775408, 2020). "Recently, the putative markers frequently being used to identify and/or isolate glioblastoma stem cells (GSCs) include: CD133, CD44, CD15, CD70 (CD27 L), S100A4, ALDH1A3, Nanog, OCT-4, SOX-2, and Nestin." (PMID 32429463, 2020). "Further supporting this claim, expression of CD44 ICD was able to induce stem cell markers in PIGPCs, primary human glioblastoma multiforme cells, and a malignant glioblastoma cell line." (PMID 33203146, 2020). "Therefore, inhibition of CD44 could be a potentially effective method for glioblastoma treatment." (PMID 31528214, 2019). "Next, to assess the potential clinical importance of the core 4‐marker signature identified (CD44, CD133, ITGA6 and CD36), we analysed publicly available glioblastoma gene expression and survival datasets from the TCGA." (PMID 30467961, 2019). "In glioblastoma, anti-miR-182 expression results in increased expression of biomarkers for proliferation and stem cell biomarkers (e.g., CCNB1, CD44, Sox2, and Nestin)." (PMID 31007608, 2019). "Our research indicated that either suppressing miR-381 or enhancing NEFL expression sensitizes glioblastoma cells to TMZ by inhibiting stemness factors (ALDH1, CD44, CKIT, KLF4, Nanog, Nestin, and SOX2)." (PMID 25605243, 2015). "In glioblastoma multiforme (GBM), the most aggressive brain tumour, CD44 inhibits the activation of the mammalian equivalent of Hippo signaling pathway and plays a key role in regulating the stress and apoptotic responses of human GBM cells." (PMID 25999819, 2015). "In this study, an up-regulation of CD44 and CD155 was demonstrated in established and early-passage cultures of glioblastoma." (PMID 22363471, 2012).